RNU2-50P (RNA, U2 small nuclear 50, pseudogene)
Gene: Small nuclear RNA gene on chromosome 9 (34,282,528 to 34,282,670, reverse strand). Ensembl gene ENSG00000222426.
Homologues: Orthologues: chimpanzee U2 (99% identical), macaque U2 (95% identical), pig U2 (75% identical), guinea pig U2 (71% identical), dog U2 (70% identical), dog U2 (19% identical), tropical clawed frog U2 (13% identical), rat LOC120103362 (10% identical). Paralogues in human: RNU2-48P (81% identical), RNU2-59P (76% identical), U2 (76% identical), RNU2-33P (76% identical), RNU2-2 (75% identical), RNU2-64P (75% identical), RNU2-6P (75% identical), RNU2-8P (75% identical), RNU2-26P (74% identical), RNU2-36P (74% identical), RNU2-3P (74% identical), RNU2-57P (74% identical), and 66 more.